SOCS1 (suppressor of cytokine signaling 1)
Diseases named in the same sentence as SOCS1 in open-access papers (continued):
Sharing a sentence is not in itself a finding about the gene and the disease.
breast carcinoma (continued). "High levels of SOCS1 have been reported in breast cancer and some melanomas." (PMID 24058673, 2013). "Furthermore, silencing of SOCS1 in breast cancer cells reestablishes the oncogenic effects of miR-155, while restoring SOCS1 expression promotes the pro-tumorigenesis function of miR-155, which indicates that miR-155 negatively regulates SOCS1." (PMID 23202960, 2012). "A recent study reported that SOCS1 expression is negatively regulated by miR-155 in breast cancers." (PMID 23231923, 2012). "Moreover, it has been shown that STAT3 inhibition by restoration of its inhibitor, suppressor of cytokine signalling (SOCS-1), results in induction of Caveolin-1, a tumour suppressor gene in breast cancer." (PMID 22567347, 2011). "SOCS1 was found to be expressed in both normal/benign breast tissue and breast cancer specimens." (PMID 20433750, 2010). "Next, we compared the expression of SOCS1–3 in tMDSCWT and normal controls at the mRNA and protein levels since the deficiency of the SOCS proteins has been reported to induce an aberrantly sustained activation of the JAK/STAT signaling pathway in human breast cancer e-MDSCs." (PMID 30083161, 2018). "SOCS1 expression was also higher among patients who remained disease free compared to all other patients who developed any type of recurrence (local or distant) or died from breast cancer during the same follow up period [mean copy number 48 vs. 4.3, 95% CI (10, 78.2), p = 0.012]." (PMID 20433750, 2010). "Growing studies have reported that SOCS1 displayed a displayed a dysregulated expression in gastric cancer, HCC, breast cancer and pancreatic cancer." (PMID 36816357, 2023). "Mechanistically, miR-155 overexpression in breast cancer cells upregulated their CXCL9/10/11 production, which was mediated by SOCS1 inhibition and increased phosphorylated STAT1 (p-STAT1)/p-STAT3 ratios." (PMID 35925680, 2022). "The regulatory network TRIM24 was involved in showed that TRIM24, YAP1, Ifn, Ifnar, SOCS1, and S100A8 together activated atherogenesis and cell viability of breast cancer cell lines through 18 genes, including AKT1, ID2, etc.." (PMID 34575874, 2021). "In addition, SNHG16/miR-30a/RRM2 axis also accelerates breast cancer cell proliferation and promote cell invasion, while miR-30a regulates liver cell proliferation and apoptosis through the suppressor of cytokine signaling 1 (SOCS-1)/JAK/STAT signaling pathway in rats with sepsis." (PMID 34895038, 2021). "In order to confirm the biological functions of CXCL9, CCR7, and SOCS1 in breast cancer, the plasmids for overexpressing CXCL9, CCR7, and SOCS1 were transfected into MCF-7/T cells." (PMID 32974144, 2020). "MiRNA-155 was overexpressed in breast cancer and downregulated the repressor SOCS1 (suppressor of cytokine signaling 1), resulting in an aberrant activation of STAT3 signaling pathway." (PMID 33133722, 2020). "MiR-221 promotes the tumor progression of cancers, such as bladder, prostate, and breast cancers, by targeting downstream molecules, including PTEN, E-cadherin, and suppressors of cytokine signaling 1, 3 (SOCS1, 3)." (PMID 31470827, 2019). "Based on the ROC curve analysis results, the SOCS1 and SOCS2 expression levels had the best specificity and sensitivity values respectively for breast cancer diagnosis." (PMID 30453988, 2018). "The SOCS1 and SOCS2 expression levels had the best specificity and sensitivity values respectively for breast cancer diagnosis." (PMID 30453988, 2018). "Dehydrocostus lactone, a plant-derived sesquiterpene lactone, inhibits cell proliferation by inducing cell cycle arrest and apoptosis through upregulating SOCS1 and SOCS3 in breast cancer cells." (PMID 28228755, 2017). "miR-155 is known to target genes such as SOCS1 and TP53INP1 enhancing proliferation in breast cancer cell lines." (PMID 25352952, 2014). "Through targeting of genes such as SOCS1, TP53BP1, and FOXO3a miR-155 is able to enhance cellular proliferation and survival of breast cancer cells." (PMID 25352952, 2014).
breast carcinoma (continued). "And the research also showed overexpression of miR-155 in breast cancer cells leads to constitutive activation of signal transducer and activator of transcription 3 (STAT3) by inhibiting SOCS1 expression." (PMID 23437123, 2013). "We determined the mRNA expression levels of SOCS1, SOCS2, SOCS3, CIS and IGF-I in 89 primary breast cancers by reverse transcriptase PCR." (PMID 17651480, 2007). "In this study, we therefore sought to elucidate the relationship between pathological and clinical parameters and the expression of the SOCS family members SOCS1, SOCS2, SOCS3, and CIS in patients with breast cancer by RT-PCR." (PMID 17651480, 2007). "The mRNA content of SOCS1, SOCS2 and IGF-I was assessed in 89 primary breast cancer samples, and of SOCS3 and CIS in 64 samples." (PMID 17651480, 2007). "The present study demonstrates that SOCS-1, -2, -3 and CIS mRNAs are expressed more strongly in human breast carcinoma." (PMID 12888825, 2003). "Research shows that the expression levels of SOCS1, SOCS2, and SOCS3 are different in breast cancer tissue, which may be related to the heterogeneity of breast cancer tissue." (PMID 39307915, 2024). "Induction of the TEM from melanoma cells, transfer of miRNAs supporting 1-integrin-NF-kB signaling from metastatic liver cancer cells, improvement of breast cancer cell motility and ECM remodeling pathways, and activation of SOCS1/JAK2/STAT3 signaling from melanoma cells." (PMID 39187523, 2024). "Indeed, STAT1 inhibitors SOCS1 and SHP1/2 (component of PTPs) are also commonly hyperactivated in breast cancer, and elevated expression of PIAS1 has been observed in prostate and breast cancers." (PMID 31658669, 2019). "Furthermore, in malignant breast cancer cells, NDRG2 overexpression specifically inhibits suppressor of cytokine signaling 1 (SOCS1) phosphorylation and induces the phosphorylation of p38 MAPK." (PMID 26506239, 2016). "In addition, we identified a novel target gene of miR-221/222, suppressor of cytokine signaling 1 (SOCS1), in human breast cancer." (PMID 24886939, 2014). "Studies in breast cancer cells suggest that MAP kinase (MAPK) p38 activation, an intermediate effector in MAPK signaling, may also play a role in upregulating SOCS1 expression." (PMID 21085662, 2010). "Similar mechanism may well be existent for SOCS1 and SOCS4-7 gene control in breast cancer and this will need further investigation." (PMID 20433750, 2010). "To evaluate the potential significance of SOCS expression in mammary carcinoma for prognosis and its association with clinicopathological characteristics we have investigated the mRNA levels of SOCS1, SOCS2, SOCS3 and CIS in a representative collection of primary breast cancers specimens." (PMID 17651480, 2007). "In conclusion, we report elevation of SOCS-1–3 and CIS in breast cancers in vivo." (PMID 12888825, 2003). "We confirmed two tumor suppressor genes, suppressor of cytokine signaling 1 (SOCS1) and cyclin-dependent kinase inhibit 1B (CDKN1B), are negatively regulated in expression by both miR-221 and miR-222, which may have potential to be therapeutic targets for basal-like breast cancer treatment." (PMID 24886939, 2014). "Likewise, miR-155 also targets and downregulates the expression of the tumor suppressor SOCS1 (suppressor of cytokine signaling 1), leading to constitutive activation of the proto-oncogene STAT3 and its ability to induce inflammatory and proliferative phenotypes in mammary tumors." (PMID 25717380, 2014). "We evaluated expression of SOCS1–3 and SOCS5 genes in breast cancer samples compared with the corresponding adjacent non-cancerous tissues (ANCTs)." (PMID 30453988, 2018).
melanoma (60 papers, 2007 to 2026). A malignant, usually aggressive tumor composed of atypical, neoplastic melanocytes. "In melanoma cell lines, the loss of suppressor of cytokine signaling-1 (SOCS-1) expression is correlated with increased STAT3 signaling and subsequent overexpression of MMP-2, basic fibroblast growth factor (bFGF), and VEGF." (PMID 39780275, 2025). "Exosomal miR-155-5p secreted by melanoma cells can induce the proangiogenic switch of cancer-associated fibroblasts (CAFs) via the SOCS1/JAK2/STAT3 pathway." (PMID 37248542, 2023). "Epigenetic inactivation due to CpG methylation of SOCS1 is frequently linked to Hepatocellular carcinoma, human gastric carcinoma, melanoma, multiple myeloma, pancreatic ductal neoplasm, and acute myeloid leukemia." (PMID 31105556, 2019). "However, recent studies have demonstrated that SOCS1 could be directly implicated in tumor suppression by blocking mitosis in melanoma cell lines." (PMID 28445952, 2017). "Importantly, STAT3 is also sensitive to inhibition by SOCS proteins and prior studies in melanoma brain metastases have suggested that loss of SOCS1 expression could promote metastasis via elevated STAT3 signaling." (PMID 20398276, 2010). "Melanoma-derived exosomal miR-155 downregulates suppressor of cytokine signaling 1 (SOCS1), an inhibitor of the JAK2/STAT3 pathway, activating JAK2/STAT3 signaling, promoting MMP-9 expression, and enhancing tumor angiogenesis." (PMID 40284474, 2025). "SOCS1 and SOCS3 are key players also implicated in melanoma cell growth and tumor development, even if controversial effects have been described." (PMID 38975347, 2024). "Consistently, SOCS1 inhibition in murine B16F10 melanoma cells has been shown to revert the tumorigenic phenotype and inhibit cell metastasis, by inducing cell-cycle arrest at S-phase and decreasing melanoma cell invasion." (PMID 38975347, 2024). "In early studies, SOCS1 was considered as a progression marker of human melanoma, being its expression related to tumor invasion, tumor thickness and stage of the disease." (PMID 38975347, 2024). "On the other hand, SOCS1 has been found to block mitosis in melanoma cell lines, by reducing levels of cell-cycle G1 phase regulators, such as cyclin D and cyclin E levels and altering M-phase protein levels." (PMID 38975347, 2024). "For instance, SOCS1 deficiency enhances the antitumor effects of IFN-α in vivo, as demonstrated in a malignant melanoma mouse model." (PMID 38711523, 2024). "Consistently, it has been proposed that melanoma cell-secreted exosomal miR-155-5p can induce the proangiogenic switch of CAFs via the SOCS1/JAK2/STAT3 signaling pathway." (PMID 35443745, 2022). "SOCS1 was demonstrated to be unfavorable for clinical outcome in patients with human melanoma and in those with acute myeloid leukemia 55-56." (PMID 33758600, 2021). "For example, melanoma cell-secreted exosomal miR-155-5p, which was selected as a survival-associated miRNA, could induce a proangiogenic switch of fibroblasts associated with cancer through improving proangiogenic factors' expression in recipient fibroblasts via SOCS1/JAK2/STAT3 signaling pathway." (PMID 33897771, 2021). "Intradermal injection of SOCS1-transfected human melanoma cell lines in nude mice resulted in fewer and smaller tumors." (PMID 34639015, 2021). "Previous studies showed the frequent silencing of SOCS1 via promoter hypermethylation in human cancer, including melanoma." (PMID 34639015, 2021).
melanoma (continued). "The conditioned medium of antigen-stimulated lung mast cells can enhance migration and invasion potentials of B16F1 melanoma cells in an SOCS1-depedent manner." (PMID 34135893, 2021). "Exosomal miR-155 derived from melanoma cells inhibits the expression of suppressor of cytokine signaling 1 (SOCS1) by targeting its 3′ UTR and activates the JAK2/STAT3 signaling pathway." (PMID 33213510, 2020). "MiR-155-containing, melanoma-derived EVs are taken up by CAFs, leading to suppressed SOCS1, increased JAK/STAT signaling and expression of pro-angiogenic factors." (PMID 32957712, 2020). "Nonetheless, there are also contradicting reports that suggest increased SOCS1 expression as an accomplice in melanoma, colorectal cancer, breast cancer, and neuroendocrine cancer." (PMID 31105556, 2019). "In conclusion, our study demonstrates that melanoma cell-secreted exosomal miR-155 can trigger normal fibroblast reprogramming into proangiogenic CAFs by decreasing SOCS1, to activate JAK2/STAT3 signaling pathway." (PMID 30285793, 2018). "The present data suggest that SOCS1 plays an important role on melanoma progression by favoring epithelial to mesenchymal transition, upregulating tyrosine-kinase receptors and matrix metallo-proteinases." (PMID 28079159, 2017). "The contribution of SOCS1 signaling to melanoma immune evasion was shown by the prophylactic s.c. inoculation of a low number of B16shR-SOCS1 viable cells, that was able to protect against rechallenge with B16F10-Nex2 melanoma cells in a syngeneic model." (PMID 28079159, 2017). "Silencing of SOCS1 protein with shRNAi lentivirus (shR-SOCS1) led to partial reversion of the tumorigenic phenotype of B16F10-Nex2 melanoma cells." (PMID 28079159, 2017). "B16shR-SOCS1, therefore, downregulated p-ERK1/2 and the expression of PD-L1, suggesting that SOCS1 is an important immune modulator in murine melanoma." (PMID 28079159, 2017). "Silencing of SOCS1 in murine melanoma cells resulted in Smads 2/3 and Smads 1/5/8 activation, simultaneously with the increased expression of MMPs in B16F10-Nex2 murine melanoma cells, by a non-canonical pathway." (PMID 28079159, 2017). "In our system a 6-fold increase of p-CREB (Ser 133) was detected in SOCS1-silenced melanoma cell line." (PMID 28079159, 2017). "An RNA microarray analysis of B16F10-Nex2 melanoma cells with SOCS1 silenced by shRNAi-SOCS1 was undertaken in comparison with cells transduced with the empty vector." (PMID 28079159, 2017). "These date indicate that SOCS1 plays an important role in melanoma development by immune-modulation of the tumor microenvironment." (PMID 28079159, 2017). "Detection of aberrantly methylated SOCS1/2, RASSF1A, MGMT, and CDKN2A in serum has been reported to have diagnostic value in patients with malignant melanoma." (PMID 28396701, 2017). "The present work shows the role of SOCS1 in murine melanoma development and the potential of SOCS1-silenced tumor cells in raising an effective anti-melanoma immune response." (PMID 28079159, 2017). "In the present study we have demonstrated that human melanoma cell lines express basal levels of SOCS1 and SOCS3 and that these proteins are further increased upon stimulation with type I and type II IFNs." (PMID 20398276, 2010). "Twenty-four hours following transduction of human melanoma cell lines with the SOCS1 and SOCS3-expressing retroviral constructs or empty PINCO vector, the expression of EGFP was confirmed in each cell line by flow cytometry." (PMID 20398276, 2010). "The interferon-responsiveness of SOCS1 and SOCS3-positive 1259 MEL melanoma cells transfected with a vector expressing siRNA constructs targeting SOCS1 or SOCS3 was next investigated." (PMID 20398276, 2010). "For example, IFN-α and IFN-γ induced SOCS3 protein expression in the A375 melanoma cell line while both SOCS1 and SOCS3 proteins were upregulated in the HT144 cell line." (PMID 20398276, 2010).
melanoma (continued). "In the present study, over-expression of SOCS1 significantly inhibited IFN-responsiveness of melanoma cells and conversely siRNA-mediated reduction of SOCS1 enhanced the IFN-response." (PMID 20398276, 2010). "Data from the present study have expanded our understanding of SOCS protein expression in melanoma and suggest that SOCS1 and SOCS3 proteins within the tumoral compartment represent a potential target that deserves investigation in future pre-clinical studies." (PMID 20398276, 2010). "In this report, the authors used an experimental model of A375 melanoma that metastasizes to the brain and demonstrated that SOCS1 expression is significantly reduced in brain metastases as compared to the original tumor." (PMID 20398276, 2010). "In this prior study, SOCS1 expression in primary tumors from melanoma patients was thought to be an indicator of poor prognosis as it correlated with Breslow thickness and Clark's Level." (PMID 20398276, 2010). "Transduced melanoma cell lines over-expressed SOCS1 and SOCS3 proteins as determined by immunoblot analysis." (PMID 20398276, 2010). "In addition, down-regulation of SOCS1 was capable to decrease the activation of different pro-tumorigenic signals in melanoma cells." (PMID 38975347, 2024). "Moreover, miR-210 also promotes EMT, and the invasion and migration of melanoma cells, by targeting negative regulators of SOCS1, resulting in constitutive activation of the NF-κB signalling pathway." (PMID 38255297, 2024). "Moreover, the transfection of miR-210 by its mimic promoted the activity of NF-κB by negatively regulating SOCS1 in melanoma cancer stem cells." (PMID 38255297, 2024). "When SOCS1 was silenced in Mel526 melanoma cells, proliferation was reduced." (PMID 38711523, 2024). "SOCS1 can further limit anti-proliferative and pro-apoptotic effects of IFNs: when downregulating SOCS1 gene expression in colon- and melanoma- cancer cell lines, IFN-γ treatment led to reduced proliferation and induced interferon-sensitive response element (ISRE)-mediated transcriptional activity." (PMID 38711523, 2024). "Furthermore, SOCS1 is silent in 50% of liver cancer cases, 44% of gastric cancer cases, 75% of melanoma cases, and 40% of hepatoblastoma primary tumours." (PMID 35610596, 2022). "In melanoma, melanoma cell-secreted exosomal miR-155 suppressed SOCS1 expression in CAFs." (PMID 36505769, 2022). "Melanoma cell–secreted exosomal miR-155-5p activated the suppressor of cytokine signaling 1/janus kinase 2/signal transduction and activator of transcription 3 (SOCS1/JAK2/STAT3) signaling pathway and induced the proangiogenic switch of CAFs." (PMID 33869017, 2021). "For example, SOCS-1 inhibited apoptosis in cardiac myocytes via ERK1/2 pathway activation varicella–zoster virus ORF12 protein inhibited apoptosis by induced phosphorylation of ERK1/2 in melanoma cells." (PMID 32759741, 2020). "Here, we observed that melanoma cell-secreted exosomal miR-155 suppressed SOCS1 expression in CAFs." (PMID 30285793, 2018). "The loss of SOCS1 expression leads to the activation of the JAK2/STAT3 signaling pathway and overexpression of MMP-2, FGF2, and VEGF and enhanced invasion and angiogenesis of melanoma cells, consequently promoting brain metastasis." (PMID 30285793, 2018). "In melanoma, it may serve as a marker for tumor progression since SOCS1 silencing leads to inhibition of metastasis and reversal of tumorigenic phenotype in vitro." (PMID 30166456, 2018). "Furthermore, aberrant DNA methylation in SOCS genes have been reported in interferon γ response in melanoma, reaching 75% in SOCS1, 44% in SOCS2, and 60% in SOCS3." (PMID 30166456, 2018). "However, melanoma cells can overcome the IFN-α effect via suppressor of cytokine signaling 1 (SOCS1), which mediates ubiquitinization and degradation of JAK." (PMID 28798748, 2017).